NEO1 (neogenin 1)
Diseases named in the same sentence as NEO1 in open-access papers (continued):
Sharing a sentence is not in itself a finding about the gene and the disease.
cancer (18 papers, 2009 to 2025). A tumor composed of atypical neoplastic, often pleomorphic cells that invade other tissues. "Given the role of NTN1/NEO1 signaling in promoting the self-renewal of pluripotent stem cells, we evaluated the possible effects of the NTN1/NEO1 axis on cancer stemness." (PMID 40777309, 2025). "Using pancreatic organoids, we demonstrate that NTN1 directly regulates PDAC growth through cancer cell NEO1 in an autocrine manner." (PMID 40777309, 2025). "While the role of NTN1/NEO1 signaling in neural development has been well-established, the effects of NEO1 activation on cancer cells remained largely unexplored." (PMID 40777309, 2025). "While we used NEO1 as an example, several other genes known to have roles in cancer proliferation and various pathway cascades were identified within these shared compartments, including EPS8, FAM92A, IRS1, and SETBP1." (PMID 37016431, 2023). "A previous report from our group, showed that NEO1 expression in NB public database is correlated with a low survival rate, indicating a possible role of NEO1 in the pathogenesis of this cancer." (PMID 33724150, 2021). "NEO1 has been reported to be deregulated in several cancer types but little is known about its specific function in cancer cells." (PMID 29137400, 2017). "NEO1 itself induces apoptosis in certain contexts but within the context of cancer, in addition to autocrine ligand production, the stroma and/or basal lamina of vessels produce Netrins, thereby increasing the capacity of cells to migrate guided by NEO1." (PMID 28038459, 2017). "Further study will be critical in determining the role and regulation of neogenin-1 in various cancer types, as well as the roles of neogenin-1, galectin-3 and HSF-1 regulation in cancer metastasis." (PMID 24930499, 2014). "The expression levels of both galectin-3 and neogenin-1 were higher in cancer tissues than in normal tissues." (PMID 24930499, 2014). "In contrast to DCC, neogenin-1 appears to have varying expression and function depending on the organ from which the cancer originated." (PMID 24930499, 2014). "Several genes that encode these proteins were upregulated in the CD26+ cancer cells: AGR2, BCMP11, CEACAM5/CD66e, CRISP3, KCNG3, KCNH8, LOX and NEO1." (PMID 20021671, 2009). "LOX and NEO1 also appeared to be expressed by NP stromal cells, which would make them less suitable as cancer biomarkers." (PMID 20021671, 2009). "NTN1 directly increases PDAC cell growth, EMT, and cancer stemness through NEO1." (PMID 40777309, 2025). "In addition to being in a situation that is easy to study and a cancer-related protein, membrane proteins like NEO1 are highly cell-type specific, with differences in 3′-UTR length playing a significant role in their regulation." (PMID 41377654, 2025). "Thus, this elevated NEO1 level suggests a selective advantage acquired by cancers cell to migrate and metastasize." (PMID 33724150, 2021). "The role of NEO1 in several cancer types has also been elucidated." (PMID 33088218, 2020). "NEO1 signaling is becoming an attractive target for use in cancer therapies." (PMID 28038459, 2017). "In cancer onset NEO1 might govern cell cycle kinetics and survival, while in aggressive tumor cells, NEO1 may function promoting cell migration." (PMID 28038459, 2017). "Also, neogenin-1 is involved in various aspects of cancer progression and metastasis." (PMID 24930499, 2014). "However, the role of neogenin-1 remains unclear because the opposite functions on cancer have been reported in several cancers." (PMID 24930499, 2014). "The Kras mutation and β-adrenergic signaling also induce tumoral NEO1 expression, establishing a tumor cell-intrinsic NTN1-NEO1-FAK axis that directly enhances EMT and cancer stemness, promoting progression to advanced PDAC and eventually to liver metastasis." (PMID 40777309, 2025).
cancer (continued). "A transwell migration assay showed that treatment of Panc02 PDAC cells with rNTN1 increased cancer cell migration, an effect that was reversed by CRISPR-mediated knockdown of Neo1 or co-treatment with the NEO1-blocking antibody." (PMID 40777309, 2025). "In conclusion, our work underscores the importance of an axon guidance molecule in cancer cell-nerve interaction and demonstrates that the NTN1/NEO1 axis drives pancreatic tumorigenesis directly and indirectly through nerves." (PMID 40777309, 2025). "For instance, a repertoire of axon-guidance molecules (e.g. netrin-1, UNC5A, NEO1, RGMA) have been shown to be dysregulated in human cancers, including colorectal cancer." (PMID 29459716, 2018). "Based on our results, we propose that NEO1 and/or NTN4 are promising targets for use anti-cancer therapies, in particular to inhibit the tumoral metastasis." (PMID 28038459, 2017). "Under the differentially expressed genes we identified several genes previously related to cancer including the up-regulated SSX1, SSX2, RXFP2, RYR2 and the down-regulated CSTA, TSPAN7, NEO1, S100A, SERPINB5 and SEPP1." (PMID 25857299, 2015). "Genetic interaction data suggest that draxin acts through Deleted in colorectal cancer (DCC) and Neogenin (Neo1), to regulate thalamocortical projections in vivo." (PMID 26659141, 2015). "In fact, reduced expression of DCC has been reported in several types of cancer (prostatic, colorectal and NB), unlike NEO1, which expression is not altered." (PMID 28038459, 2017). "Thus, a cancer cell that has lost its NEO1/DCC receptor is thought to be able to move away from its normal environment with impunity." (PMID 30858446, 2019). "NEO1 and NTN4 are expressed in sites where NB originates, such as in the DRG of the embryonic neural crest, and we hypothesize that their functions persist throughout cancer progression, as a result of an impairment in the normal developmental signaling." (PMID 28038459, 2017). "Although previous studies suggested that NTN1 promotes cancer cell growth and EMT through the UNC5B receptor, we found that NEO1, rather than UNC5B, was largely upregulated during mouse pancreatic tumorigenesis." (PMID 40777309, 2025).
tumor (15 papers, 2007 to 2025). "The Kras mutation induces NTN1 secretion from the pancreatic epithelium, which increases tumor-associated sympathetic axonogenesis via nerve NEO1." (PMID 40777309, 2025). "Consistently, in GSE41258 dataset and Zhongnan Hospital tissues, the expression of NEO1 was proved to be significantly and negatively associated with the tumor stage for CRC." (PMID 33088218, 2020). "Conversely, loss of DCC expression, a homolog of NEO1, correlates inversely with the degree of NB dissemination, acting in this context as a tumor suppressor." (PMID 28038459, 2017). "In many of these cases, the deregulation of NEO1 is associated with elevated tumor aggressiveness and progression." (PMID 29137400, 2017). "We next investigated the underlying mechanism of NEO1-induced suppression of tumor growth." (PMID 36746934, 2023). "NEO1 was shown to be expressed in NB tumors; mostly, tumor-cell-associated staining was detected." (PMID 36231134, 2022). "In a splenic injection model using Neo1-knockdown and control mT4 cells, Neo1 knockdown prolonged mouse survival and decreased the tumor burden of PDAC liver metastasis, as shown by histology and reduced liver weight." (PMID 40777309, 2025). "The tumor formation of the human HCT 116 cells emerged after 4 weeks, while delayed tumorgenicity and smaller tumor size were observed in NEO1-overexpressing group." (PMID 36746934, 2023). "After s.c. injection of the cells to mice, primary tumor growth was unaffected; instead, NEO1 downregulation impaired spontaneous spreading to the spleen, kidneys, liver (the cells were found exclusively in lungs)." (PMID 36231134, 2022). "Collectively, our data show that NEO1 is expressed in NB patient samples, mostly in tumor cells, and persists throughout different NB stages." (PMID 33724150, 2021). "The results confirmed that NEO1 was down-regulated in CRC tumor tissues when compared with non-tumor tissues, both in mRNA level (p = 0.0038, n = 53) and protein level." (PMID 33088218, 2020). "The mice immunized with BALB/cJ-derived BMDCs, Neo1, in the presence of 9D9 IgG2b rejected the Meth A tumor challenge completely (100%) and rapidly (< 20 days)." (PMID 30030558, 2018). "The impaired wound closure in shNEO1 cells confirmed the importance of NEO1 in NB cell migration, and thus in tumor migration." (PMID 28038459, 2017). "Nonetheless, further analysis of NEO1 variations in BCC subtypes is necessary in order to explain different tumor behaviors." (PMID 29137400, 2017). "In order to determine the spatial distribution of NEO1 within the neoplasm, we screened both sporadic and Gorlin-related BCCs by IHC." (PMID 29137400, 2017). "While non- aggressive human BCC subtypes display high NEO1 expression, aggressive human BCC subtypes present with lower levels of NEO1, similar to GLI1, suggesting a possible role of SHH/GLI/NEO1 signaling in tumor aggressiveness." (PMID 29137400, 2017). "Comparison of IHCs of control skin and BCC reveal that NEO1 is highly expressed in tumor sections compared to control skin." (PMID 29137400, 2017). "Tumor cell NEO1 expression was also increased by ISO treatment in KC mice." (PMID 40777309, 2025). "Similar to the mT4 cell findings, Neo1 knockdown in Panc02 cells improved mouse survival, decreased tumor-derived luciferase signals and histological tumor areas, and reduced Ki-67+ proliferating tumor cells in the splenic injection model." (PMID 40777309, 2025). "Co-immunofluorescence showed that NTN1 and NEO1 were co-expressed in tumor cells in KPC mice." (PMID 40777309, 2025). "Eight tumor tissues exhibited significantly lower expression of NEO1 at mRNA level." (PMID 36746934, 2023). "Furthermore, we quantified the expression of NEO1 between tumor tissue and tumor-adjacent normal tissue in eight randomly selected CRC biopsies." (PMID 36746934, 2023). "Furthermore, NEO1 expression is mostly restricted to tumor cells and is persistent in all tumoral stages analyzed." (PMID 33724150, 2021).
tumor (continued). "Furthermore, in Zhongnan Hospital CRC tumor tissues, lower expression of NEO1 was correlated with worse T stage (p = 0.003), M stage (p = 0.023) and clinical stage (p = 0.048)." (PMID 33088218, 2020). "Further research direction may focus on the effects of NEO1 on inflammation within tumor microenvironment." (PMID 33088218, 2020). "In total, our findings demonstrated that NEO1 could be a prognostic biomarker and regulate tumor progression in CRC." (PMID 33088218, 2020). "Considering that NEO1 is involved in neuronal cell migration, we aimed to address whether this function was relevant in the tumor context and if it was dependent of its ligand NTN4." (PMID 28038459, 2017). "Although NEO1 and its ligands are involved in tumor progression, their precise role in tumor cell survival and migration remain unclear." (PMID 28038459, 2017). "In sporadic BCC, we observed that NEO1 was uniformly expressed throughout the tumor lesions." (PMID 29137400, 2017). "To determine whether NTN4 acts as a survival factor specifically through NEO1 or as a general survival factor, we overexpressed TrkC, a dependence receptor that acts as a tumor suppressor in NB and repeated TUNEL assays." (PMID 28038459, 2017). "We propose that NEO1 may be important in tumor onset and is then down-regulated in advanced BCC or aggressive subtypes." (PMID 29137400, 2017). "Having assessed the expression and the interaction of NEO1 and NTN4 in both NB tumors and cell lines, we next decided to evaluate the potential contribution of the NEO1/NTN4 complex signaling in a variety of processes associated with tumor progression." (PMID 28038459, 2017). "Using transwell chemotaxis assays, we examined the function of NEO1 in sensing and guiding tumor NB cells, and analyzed whether NTN4, a known chemotactic molecule, influenced this process." (PMID 28038459, 2017). "NEO1 is functionally categorized as a tumor-suppressor gene and may be involved as a regulatory protein in the transition of undifferentiated proliferating cells to their differentiated state." (PMID 17711579, 2007). "However, whether and how NEO1 regulated inflammatory within tumor microenvironment of CRC remained unclear and needed further exploration." (PMID 33088218, 2020). "Further results validated that NEO1 mRNA and protein expression were both significantly lower in CRC tumor tissues than in the adjacent tissues in our clinical samples." (PMID 33088218, 2020). "NEO1 and DCC are also tumor suppressors that can inhibit metastasis by acting as dependence receptors." (PMID 30858446, 2019). "In vivo analysis, using the chicken embryo chorioallantoic membrane (CAM) model, showed that NEO1 and endogenous NTN4 are involved in tumor extravasation and metastasis." (PMID 28038459, 2017). "We expanded our analysis of NEO1 expression by performing quantitative analysis of NEO1 mRNA levels in both human control skin and in a variety of sporadic BCC tumor samples." (PMID 29137400, 2017). "Furthermore, the present study found a strong correlation between the expression of target genes (IL10RB, INHBB, NEO1, PIK3R1, BCL2, ID4, and INHBA) and the infiltration of tumor-killing cells into the tumor immune microenvironment in HNC." (PMID 40647469, 2025). "To further validate the expression level of NEO1, we collected 53 pairs of tumor tissues and adjacent non-tumor tissues in Zhongnan Hospital of Wuhan University." (PMID 33088218, 2020). "After examining the potential role of endogenous NEO1 and NTN4 participating in apoptosis and cell migration, we wanted to ascertain whether they also participate in primary tumor formation and metastasis in vivo." (PMID 28038459, 2017). "According with Versteeg data set, there is not difference in NEO1 expression in tumor samples with or without MYCN amplification." (PMID 28038459, 2017).
tumor (continued). "NEO1 presented with a strong cytoplasmic and nuclear expression profile in non-aggressive tumor tissues, similar to the staining of NEO1 in basal cells of control mouse skin." (PMID 29137400, 2017). "In addition, we assessed the protein abundance of NEO1 and ligands in a small cohort of sporadic human BCC tumor samples by WB." (PMID 29137400, 2017). "Compared to tumors growth made from negative control LacZ shRNA expressing AGS cells, the neogenin-1 ablation by both shRNAs showed reduced tumor growth in xenografted mice." (PMID 24930499, 2014). "We revealed the possible role of NEO1 expression levels in inter-tumor heterogeneity, whether there were the genomic, non-genomic, stemness and microenvironment heterogeneity within a single CRC tissue needed further unveiling." (PMID 33088218, 2020). "This may be indicative that NEO1 is a negative marker for tumor aggressiveness and we would expect a decrease in its expression along tumor progression." (PMID 29137400, 2017). "Therefore, the low NEO1 expression of the specific non-aggressive BCC samples may be as a result of patient-specific variables or due to the tumor's transition from a non-aggressive to an aggressive tumor." (PMID 29137400, 2017). "Since NEO1 is related to cell-cell adhesion, its downregulation could promote epithelial-mesenchymal transition in the aggressive subtypes of BCC and explain the histology of this neoplasms where tumor cells form desegregated islands compared to big nodules of non-aggressive subtypes." (PMID 29137400, 2017). "While NEO1 is significantly lower in aggressive BCC subtypes, we also detected low levels in specific non-aggressive BCC tumor samples." (PMID 29137400, 2017).
vasculopathy (3 papers, 2022 to 2023). "NEO1-deficient mice have also recently been shown to have moyamoya-like vasculopathy, particularly the development of small, leaky, thin blood vessels within the cerebral cortex." (PMID 35846951, 2022).
infection (2 papers, 2022 to 2025). The state of being infected such as from the introduction of a foreign agent such as serum, vaccine, antigenic substance or organism. "Here, we performed proximity labelling centered on epsin 1 during infection and uncover Neo1 as a potential IAV internalization receptor." (PMID 40623098, 2025). "From our analysis of the interactome hits for plasma membrane localization and infection-induced epsin 1 vicinity, Neo1 emerged as a promising candidate for an internalization receptor." (PMID 40623098, 2025). "The depletion of Neo1 expression reduced infection of reporter IAVs of multiple subtypes (H1N1, H2N2 and H5N1) as well as authentic virus and its proviral function could be confirmed in primary lung fibroblast cells." (PMID 40623098, 2025). "Overall, we conclude that Neo1 plays a proviral role in infection of IAVs of multiple subtypes." (PMID 40623098, 2025). "Given that Neo1 can co-localize with IAV at early times post-infection and affect virus entry, this suggests that it may act as a potential IAV receptor." (PMID 40623098, 2025). "We showed that Neo1 is a proviral host factor that can interact with A/WSN/33 IAV through its N-linked glycosylations, co-localize with incoming virus at early times post-infection and affect viral entry." (PMID 40623098, 2025). "Furthermore, there were nine proteins that were specifically detected at 7 days post-infection (Saa2, Trappc1, Cxadr, Armc8, Hbxip; Lamtor5, Prppsap2, Usp46, Pcdh10, Neo1)." (PMID 36061859, 2022). "Moreover, human recombinant Neo1 was found to bind IAV with a KD of 21 ± 14 nM by atomic force microscopy and Neo1 could co-localize with incoming IAV at early times post-infection, as well as affect viral entry." (PMID 40623098, 2025). "As Neo1 is expressed at the primary site of infection, can interact with IAV and co-localize with the virus at early times post-infection and its depletion impairs IAV entry, this study highlights its potential as one of the IAV internalization receptors." (PMID 40623098, 2025). "We observed that the peak of IAV and clathrin co-localization occurs at 15 minutes post-infection, which coincides with a less prominent peak describing IAV, clathrin and Neo1 co-localization." (PMID 40623098, 2025). "Next, we evaluated the co-localization of Neo1 and IAV at early stages of infection through confocal microscopy." (PMID 40623098, 2025). "We also showed that Neo1 can interact with IAV with high affinity, co-localize with incoming virus at early infection stages and affect viral entry, which is reduced in its absence." (PMID 40623098, 2025). "We observed that surface Neo1 can co-localize with incoming IAV at 2 and 5 minutes post-infection." (PMID 40623098, 2025). "Since VSV is internalized by CME but does not require Neo1 for entry, we next evaluated the localization of Neo1, clathrin and VSV at early times post-infection to provide context." (PMID 40623098, 2025). "Lastly, Neo1 could co-localize with incoming IAV in non-permeabilized and permeabilized samples at early times post-infection and its depletion reduced viral entry, highlighting its potential as a virus receptor." (PMID 40623098, 2025). "To further assess the potential of Neo1 as an IAV receptor, we infected A549 cells stably overexpressing Neo1 (LV-Neo1) with A/WSN/33 at MOI 100 and evaluated their localization at 2 and 5 minutes post-infection under non-permeabilized conditions via immunofluorescence." (PMID 40623098, 2025).